SMAP2 (small ArfGAP2)
Description:
GTPase activating protein that acts on ARF1. Can also activate ARF6 (in vitro). May play a role in clathrin-dependent retrograde transport from early endosomes to the trans-Golgi network (By similarity).
Synonyms: SMAP1L
Tractability: PROTAC: ubiquitination databases record sites on it; its protein half-life has been measured.
Gene: Protein-coding gene on chromosome 1 (40,344,850 to 40,423,326, forward strand). Ensembl gene ENSG00000084070.
Subcellular location: Cytoplasm
Subcellular location (Human Protein Atlas): Cytosol; Nucleoplasm
Gene Ontology:
Molecular function: protein binding; GTPase activator activity
Cellular component: cytosol; cytoplasm
Genetic constraint (gnomAD): Loss-of-function variants: 14 observed, 45.7 expected, observed/expected ratio (o/e) 0.31, 90% interval 0.2 to 0.48. The upper end of that interval is the gene's LOEUF score, 0.48, which puts it in group 2 of 6, group 1 being the genes least tolerant of losing a copy. Missense variants: 349 observed, 521.39 expected, observed/expected ratio (o/e) 0.67, 90% interval 0.61 to 0.73. Synonymous variants: 146 observed, 175.4 expected, observed/expected ratio (o/e) 0.83, 90% interval 0.73 to 0.95.
Homologues: Orthologues: chimpanzee SMAP2 (100% identical), macaque SMAP2 (99% identical), rabbit SMAP2 (97% identical), dog SMAP2 (97% identical), pig SMAP2 (96% identical), guinea pig SMAP2 (96% identical), mouse Smap2 (96% identical), rat Smap2 (96% identical), tropical clawed frog smap2 (64% identical), zebrafish smap2 (55% identical), Drosophila melanogaster CG8243 (35% identical). Paralogues in human: SMAP1 (48% identical), ADAP1 (20% identical), ADAP2 (19% identical), ARAP1 (19% identical), ARAP2 (18% identical), ARAP3 (18% identical), AGFG1 (16% identical), ACAP2 (15% identical), ASAP2 (15% identical), AGAP2 (14% identical), AGAP3 (14% identical), ASAP1 (14% identical), and 16 more.
Diseases named in the same sentence as SMAP2 in open-access papers:
SMAP2 is named in the same sentence as 7 diseases in open-access papers, as found by Europe PMC text mining. Sharing a sentence is not in itself a finding about the gene and the disease. The quoted sentences say what the papers report.
asthenozoospermia (1 paper, 2021). "In mammals, SMAP2 is necessary for spermiogenesis, where SMAP2-deficient mice have been shown display male infertility, globozoospermia, asthenozoospermia, and abnormal acrosome formation." (PMID 33777090, 2021).
brain arteriovenous malformations (1 paper, 2023). "Finally, SCENIC analysis identified TWIST2, MTA3, and SMAP2 as possible key EndMT EC differentiation-regulating TFs, among which TWIST2 has been confirmed as the key TF in EndMT ECs in brain arteriovenous malformations." (PMID 37853464, 2023).
cancer (2 papers, 2019). A tumor composed of atypical neoplastic, often pleomorphic cells that invade other tissues. "Another observation is that some gene identified as a Up target in one cancer type is also identified as a Down target in another cancer type (e.g., SMAP2 )." (PMID 31227749, 2019).
SMAP2 also shares sentences with these, for which no sentence is quoted: COVID-19 (1 paper); endometriosis (1); Globozoospermia (1); male infertility (1).